INS (insulin)
Diseases named in the same sentence as INS in open-access papers (continued):
Sharing a sentence is not in itself a finding about the gene and the disease.
diabetes (continued). "Type 1 Diabetes Mellitus (T1DM) is a chronic autoimmune disorder characterised by the destruction of insulin-producing β cells in the pancreas." (PMID 39408940, 2024). "Diabetes is characterised by the intricate interactions of several processes, such as insulin signalling, glucose metabolism and inflammatory responses." (PMID 38982323, 2024). "This often forces children to self-administer insulin, resulting in suboptimal HbA1c levels and overall inadequate diabetes management during school hours." (PMID 39195172, 2024). "Cinnamaldehyde also shines in metabolic regulation, enhancing glucose uptake and insulin sensitivity, crucial for managing diabetes and obesity." (PMID 38903995, 2024). "Thirty-eight gene sets showed significant enrichment (q value < 0.01), 25 of which were related to metabolic phenotypes (for example, ‘diabetes’, ‘hyperglycaemia’, ‘overweight’, ‘waist’, ‘insulin’, ‘c peptide’)." (PMID 38278947, 2024). "Injection of insulin as treatment for diabetes induces neurotrophic factors (BDNF) in hippocampus which has an improving effect on memory performance of Morris water maze test." (PMID 38528644, 2024). "Our results suggest the crucial role of AKT in NORM3 effects, consistently with the involvement of AKT activation in improving insulin sensitivity, regulation of gluconeogenesis, and recovery of hepatic oxidative redox balance in diabetes and obesity." (PMID 39474783, 2024). "Several studies have shown that the supplementation of glutamine resulted in a significant reduction in plasma glucose levels and increases in plasma and pancreatic insulin levels, suggesting the beneficial effects of glutamine in diabetes." (PMID 39629074, 2024). "Improved glycemic control with sulphonylurea treatment has been demonstrated in individuals with shorter durations of diabetes and lower HbA1c and BMI at the time of transition to insulin." (PMID 39420387, 2024). "These risk factors include female gender, a history of stroke, longer duration of diabetes, poor glycemic control, complications related to neuropathy and nephropathy, as well as the use of a combination of oral hypoglycemic agents and insulin." (PMID 39529774, 2024). "SCFAs can effectively reduce the incidence of enteritis, cardiovascular disease, colon cancer, obesity, and diabetes, and also play an important role in maintaining the balance of energy metabolism (mainly glucose metabolism) and improving insulin tolerance." (PMID 38257292, 2024). "The discovery of insulin was a turning point in not only understanding diabetes but also dispelling many misconceptions that had clouded the field." (PMID 39691108, 2024). "Among the recent advancements are glucagon-like peptide-1 (GLP-1) agonists and glucose-dependent insulinotropic peptide (GIP) dual agonists and once-weekly insulin, which offer promising avenues for diabetes management." (PMID 39335457, 2024). "Type 2 diabetes mellitus (T2DM) is the most common type of diabetes mellitus in adults and results from insulin resistance and an insulin secretory defect due to beta cell dysfunction." (PMID 39010018, 2024). "In humans, alterations to INS signaling pathways often result in debilitating metabolic diseases, including diabetes." (PMID 38313028, 2024). "Long-acting insulin formulations have greatly enhanced patient quality of life and glycemic control in diabetes treatment." (PMID 39458672, 2024). "Teacher victimization of students can lead to poor adherence to diabetes treatment through missed insulin administration or blood glucose monitoring, negatively affecting diabetes management at school." (PMID 39334618, 2024). "The benefits of improved insulin sensitivity persist for 16 hours after exercise in both healthy subjects and patients with Type 2 Diabetes Mellitus (T2DM)." (PMID 38962677, 2024).
diabetes (continued). "The introduction of proteins and peptides (PPs) in modern medicine is connected with the discovery of insulin in the twenties of the 20th century and the beginning of effective treatment of diabetes mellitus." (PMID 38255888, 2024). "One possible explanation is that those with hypertension and diabetes are already metabolically impaired, displaying decreased insulin sensitivity." (PMID 38685122, 2024). "Diabetes is a chronic disease characterized by abnormally high blood glucose levels due to impaired insulin action or secretion." (PMID 38175421, 2024). "Diabetes antigens include peptides formed from proteins recognized by the autoantibodies commonly seen in T1D patients, insulin (IAA), glutamic acid decarboxylase 65 (GAD65) Islet antigen 2 (IA-2), and Zinc transporter 8 (ZnT8)." (PMID 39328411, 2024). "The pathophysiology of diabetes, which involves multiple hormones such as insulin, glucagon, and growth hormone, is complex and crucial to understand for effective prevention and management." (PMID 39371721, 2024). "Depletion of B cells by anti-CD20 prevented diabetes in NOD mice and delayed the loss of insulin in T1D in humans, which was more effective in younger patients, underscoring the contribution of B cells to T1D pathology." (PMID 38487540, 2024). "Upon the development of the nano-network (NNS) loaded with insulin, it was administered into mice with diabetes, showcasing a robust cohesive attribute that facilitated effortless shaping and administration of the medication." (PMID 39771551, 2024). "The game provides comprehensive education for children on various aspects of diabetes, including technical skills such as measuring blood glucose levels and administering insulin, as well as explanations of the nature of the disease." (PMID 38713496, 2024). "Ultimately, the advancement of light-activated insulin has the potential to transform diabetes management completely." (PMID 38542928, 2024). "In this sense, findings from previous studies have demonstrated a range of responses to insulin treatment in reversing/attenuating cardiac dysfunctions in STZ experimental diabetes." (PMID 38794147, 2024). "Diabetes represents a chronic metabolic disorder characterized by insufficient insulin production by the pancreas or impaired utilization of the produced insulin." (PMID 39194658, 2024). "Meta-inflammation during pre-diabetes induces IR, and to meet up with the increased insulin demand, pancreatic beta cells are coaxed to produce excess insulin." (PMID 38327565, 2024). "Limited insulin release from pancreatic β-cells underpins type 2 diabetes pathology and the global epidemic of diabetes is expected to affect 643 million by 2030." (PMID 39546458, 2024). "Structured diabetes education (SDE) has been a successful therapeutic modality for all patients with type 1 diabetes mellitus (T1DM) on the basal-bolus regimen of intensive insulin therapy (IIT) over the past decades." (PMID 39611060, 2024). "Regarding the 72 patients with individual data, 8% (n = 6) remained insulin-independent from diabetes onset until the median follow-up time of 1 year (3 days–3 years) after initiation of thiamine." (PMID 39025920, 2024). "Every patient with insulin-treated diabetes, especially children and young patients with type 1 diabetes, should be provided with appropriate SMBG equipment." (PMID 39063405, 2024). "Diabetes is managed by a healthy, low-calorie diet with restricted carbohydrate intake, regular aerobic exercise, and a blood sugar level-adjusted insulin dose." (PMID 38883102, 2024). "It was also significantfor mitral valve endocarditis due to Staphylococcus aureus in2005, insulin-requiring type 2 diabetes mellitus, obesity, and obstructive sleepapnea." (PMID 39422216, 2024). "Insulin therapy plays a pivotal role in the treatment of diabetes mellitus, a chronic disease affecting, according to the World Health Organization (WHO) data, 537 million people around the world." (PMID 38255888, 2024).
diabetes (continued). "Conversely, insufficient levels of 25(OH)D can contribute to insulin resistance and the development of diabetes, given its vital role in insulin secretion, the maturation of insulin-secreting cells, and overall insulin function." (PMID 39415789, 2024). "As in the case of sensors, insulin pumps were also considered to ease the control of blood glucose levels and implicitly the diabetes itself (Q28), as 70% of the respondents have witnessed a better, more flat glycemic profile (Q29)." (PMID 39376804, 2024). "Specifically, diabetes induction (T2DM) significantly reduced plasma insulin levels to 2.140 ± 0.091 (p < 0.001) from the control value of 3.725 ± 0.208." (PMID 39766390, 2024). "The primary role of insulin is to regulate glucose metabolism for the treatment of diabetes, which is a chronic disease." (PMID 39190215, 2024). "Diabetes mellitus is a chronic health condition characterized by high blood glucose due to either the inability of the pancreas to produce adequate insulin or the body’s resistance to available insulin." (PMID 39190716, 2024). "The effects of Berberis aristata plus Silybum marianum were also studied in 85 T1DM (type 1 diabetes mellitus) patients on insulin therapy for a minimum of three months who were also following a low-calorie diet and increasing physical activity." (PMID 39796448, 2024). "Nevertheless, given the large number of diabetes clinics in Italy and their homogeneous geographic distribution, the referral of patients needing insulin therapy to specialist care is common practice." (PMID 38767675, 2024). "Individuals prone to developing diabetes or with overt type 2 diabetes show irregular oscillations of plasma insulin." (PMID 38791525, 2024). "Especially, in cases of PW syndrome, phenotype management of double diabetes needs a multidisciplinary approach, including weight management, insulin sensitizers, behavioral therapy, and counseling." (PMID 39135667, 2024). "Louis Children's Hospital became the first person with diabetes in the United States to be treated with insulin." (PMID 39718705, 2024). "Type 2 diabetes mellitus (T2DM), which is marked by hyperglycemia due to insulin resistance and insufficient insulin secretion, represents a significant percentage of diabetes cases." (PMID 39011198, 2024). "The dysregulation of insulin signaling in women with metabolic syndromes including diabetes exhibits poor pregnancy outcomes that are poorly understood." (PMID 38790245, 2024). "Diabetes is one of the most serious illnesses in the world and arises because of inadequate insulin generation by the pancreas or ineffective usage of insulin by the body." (PMID 39683757, 2024). "In pre-diabetes subphenotyping, adequate methods for measurement of insulin secretion are similarly important for capturing key differences between pre-diabetes subphenotypes." (PMID 39013634, 2024). "In fact, metagenomic analyses revealed the existence of EVs of the Proteobacteria phylum in the serum of individuals with diabetes, which inhibits insulin-induced activation of the insulin receptor substrate 1 in HFD-fed mice." (PMID 39085351, 2024). "Secure messaging solidifies diabetes self-management for weekly review of blood glucose in order to determine the need for insulin therapy." (PMID 38686560, 2024). "Abnormally delayed gastric emptying, sometimes associated with clinical symptoms (ie, “diabetic gastroparesis”), occurs in ∼30% of people with longstanding, suboptimally controlled, insulin-treated diabetes." (PMID 39568409, 2024). "The dietary management of insulin resistance or diabetes should include limiting postprandial insulin levels." (PMID 38474713, 2024). "A hybrid closed-loop system (HCL) is an advanced diabetes management technology that automates the delivery of insulin based on real-time continuous glucose monitoring (CGM)." (PMID 38659016, 2024).
diabetes (continued). "Collectively, these data identify multiple proteins that correlate with the insufficient glucose-stimulated insulin secretion in islets from donors with diabetes." (PMID 38959864, 2024). "Accordingly, in a recent clamp-based study in subjectswithout diabetes, there was greater deterioration of insulin sensitivity and greater fat accumulation in females than in males." (PMID 38218814, 2024). "In the subgroup of patients with diabetes, individuals with overweight and obesity were less likely to receive insulin therapy and to have peripheral vascular disease, multi-vessel coronary disease than normal-weight individuals (P < 0.05)." (PMID 38365597, 2024). "Metformin, an insulin sensitizer, has been widely used in conjunction with diet and exercise for glycemic control in type 2 diabetes mellitus patients." (PMID 38769300, 2024). "This impact is particularly significant for younger children, who rely on their environment to manage their diabetes and administer insulin doses prior to meals." (PMID 38892551, 2024). "Diabetes mellitus occurs as a result of a dysfunction within the pancreatic beta-cells that produce insulin, leading to abnormal carbohydrate metabolism and hyperglycemia." (PMID 38606021, 2024). "Diabetes is principally characterized by impaired insulin signaling cascades resulting from insufficient insulin production [type 1 diabetes (T1D)] or insulin resistance (type 2 diabetes, T2D) (9, –, 12)." (PMID 38526063, 2024). "Several protocols have been developed to generate hPSC-derived pancreatic progenitors and insulin-producing islet-like clusters capable of preventing or reversing chemically induced diabetes in rodents." (PMID 38167219, 2024). "Current diabetes treatments include lifestyle interventions, oral hypoglycemic agents, and insulin therapy." (PMID 39483785, 2024). "Type 2 diabetes mellitus (T2DM) is a chronic systemic metabolic disorder characterized by elevated blood glucose levels caused by insulin resistance (IR) and/or impaired insulin secretion." (PMID 39534794, 2024). "Past medical history included essential hypertension, type 2 diabetes mellitus managed with insulin, osteoarthritis, and morbid obesity (BMI: 41 Kg/m2)." (PMID 38737669, 2024). "As a result, the level of insulin secretion decreases by 0.7% with age, further increasing the incidence of diabetes in the elderly." (PMID 39062777, 2024). "Many studies, including those from our center, showed that short-term intensive insulin therapy (SIIT) can induce long-term remission of diabetes in early-stage T2D patients." (PMID 38476668, 2024). "Alterations in insulin signalling, gluconeogenesis, and glucose uptake in key organs critically involved in glucose homeostasis, such as the liver and kidneys, occur in diabetes." (PMID 39339687, 2024). "A new paradigm in the management of diabetes mellitus evolved following the introduction of continuous subcutaneous insulin infusions (CSII) into clinical practice." (PMID 39575358, 2024). "The analysis also revealed decreases in fasting insulin and HbA1c levels, indicating improved glycemic control in individuals with diabetes." (PMID 39195249, 2024). "Thanks to major advances in blood glucose monitoring and insulin delivery technologies, a remarkable leap forward has been made in the management of diabetes." (PMID 38337523, 2024). "We here report the case of a female patient with suspected severe Cushing ́s syndrome associated with melanoderma, arterial hypertension resistant to triple therapy and unbalanced diabetes treated with insulin therapy." (PMID 38737225, 2024). "Wearable insulin delivery devices such as the Omnipod Insulin Management System (Insulet Corp., Acton, MA) are popular among people living with diabetes." (PMID 37098714, 2024). "Fruits of Bitter gourd improve glycemic control and stems-leaves of Bitter gourd increase plasma insulin concentrations in an obese pig model for mild diabetes." (PMID 38498469, 2024).
diabetes (continued). "Such communication is particularly important when DM progresses and requires treatment modification such as adding new diabetes medications (for example, insulin) or increasing the dosage of current medications." (PMID 38338237, 2024). "Diabetes mellitus (DM) is a chronic, metabolic disease characterized by hyperglycemia due to a decrease in insulin production or insulin sensitivity that eventually leads to severe damage to many of the body's systems." (PMID 39246956, 2024). "In conclusion, ILP-Ap04 showed strong hypoglycemic activity in the STZ-induced zebrafish model of diabetes, and its activity was comparable to that of human insulin." (PMID 38535452, 2024). "In the present study, an insulin-loaded alginate and chitosan-coated LDH nanocomposite system (Alg-Chi-LDH@INS) has been first developed for the oral insulin treatment of diabetes." (PMID 38214820, 2024). "In the COMISAIR study, which included 94 participants with type 1 diabetes, improvement in the metabolic control of diabetes was achieved after the use of CGM systems in patients treated with both insulin pumps and pens." (PMID 39202265, 2024). "This study’s discovery of an inverse relationship between the use of insulin secretagogues or insulin and the age of death suggests that the prevention of life-threatening hypoglycemia is crucial for individuals with diabetes." (PMID 38592103, 2024). "We found that among the 624 individuals, 77 were taking metformin and 10 were taking insulin for diabetes." (PMID 38585953, 2024). "High fat diet and a low dose of STZ were used to induce both peripheral insulin resistance as well as impairment of insulin production and secretion via partial degeneration of β-cells to mimic the natural pathophysiology of type 2 diabetes mellitus." (PMID 39033184, 2024). "As for diabetes control, the ratio of patients requiring insulin injection were similar between BMI groups (40.0% vs. 42.2% vs. 45.7 %)." (PMID 39058301, 2024). "Another example is the application of closed-loop therapy for diabetes management, in which the biosensor monitors glucose levels and a controlled micro insulin pump provides personalised treatment." (PMID 39194620, 2024). "Intensive glycemic management reverses hyperfiltration, particularly in type 1 diabetes mellitus (T1DM) with insulin therapy and well controlled blood glucose levels." (PMID 38540270, 2024). "Diabetes was determined by previous doctor diagnosis, current use of glucose-lowering medication (including traditional Chinese medicine, Western medicine, insulin injections, etc.), or hemoglobin A1c levels ≥6.5%, fasting blood glucose ≥126mg/dL." (PMID 38715126, 2024). "Diabetes mellitus is attributed to dysfunctions in both the secretion and physiological activity of insulin marked by elevated plasma glucose levels, termed hyperglycemia." (PMID 39000103, 2024). "Additional benefits of ARNIs included an improvement in symptoms, an improvement in quality of life, a reduction in the incidence of diabetes requiring insulin treatment, a reduction in the decline of GFR and a reduced rate of hyperkalemia." (PMID 39200914, 2024). "Keywords in the green cluster, such as “insulin resistance,” “sensitivity,” “skeletal muscle,” “diabetes,” and “expression,” were particularly prominent." (PMID 39737158, 2024). "Overall, 31 (11.74%) patients presented with prediabetes, 58 (21.97%) presented with diabetes mellitus type 2 treated with oral hypoglycemic medications, and 4 (1.52%) had diabetes mellitus type 2 treated with insulin." (PMID 39457527, 2024). "To investigate the role of TRPC channels in long-term diabetic complications, we induced diabetes in mice using a streptozotocin protocol where chronic hyperglycemia was controlled by applications of long-acting insulin." (PMID 39375537, 2024).